SLC26A4 (solute carrier family 26 member 4)
Diseases named in the same sentence as SLC26A4 in open-access papers (continued):
Sharing a sentence is not in itself a finding about the gene and the disease.
presbycusis (3 papers, 2018 to 2021). Bilateral hearing loss caused by progressive degeneration of cochlear structures and central auditory pathways, typically associated with the aging process. "The methylation levels of SLC26A4 are significantly higher in patients with presbycusis and the methylation at the SLC26A4 promoter can predict the risk of presbycusis." (PMID 34136553, 2021). "Moreover, hypermethylation of CpG sites in the promoter region of SLC26A4 (DFNB4) and P2RX2 (DFNA41) genes resulted in increased risk for presbycusis in men, and a down-expression in elderly women with presbycusis, respectively." (PMID 30131691, 2018).
syndromic (3 papers, 2016 to 2025). "Children with SLC26A4 mutations tended to perform relatively well, whereas syndromic cases such as CHARGE or Down syndrome showed poorer thresholds and absent WRS." (PMID 41303275, 2025).
thyroid hypoplasia (3 papers, 2016 to 2024). Thyroid hypoplasia is a form of thyroid dysgenesis characterized by incomplete development of the thyroid gland that results in primary congenital hypothyroidism, a permanent thyroid deficiency that is present from birth. "In some cases, thyroid hypoplasia can also be found in patients with biallelic SLC26A4 mutations." (PMID 26886089, 2016).
breast carcinoma (2 papers, 2014 to 2024). "In MCF-7 breast cancer cells, SLC26A4 is expressed and transports I−." (PMID 38673775, 2024). "However, the mRNA and protein expression of SLC26A4 were lower in tumoral regions than in peri-tumoral regions in patients with breast cancer." (PMID 38673775, 2024). "Although decreased SLC26A4 expression is a common pattern in prostate, thyroid, and breast cancers, the relationship between SLC26A4 and tumors has not been fully demonstrated." (PMID 38673775, 2024). "However, some general trends are observed across all breast cancer subtypes: SLC4A1, SLC4A4, SLC26A3, and SLC26A4 seem to be consistently down-regulated, while SLC4A5 is up-regulated, in all breast cancer subtypes compared to normal breast tissue." (PMID 24795638, 2014).
cardiac hypertrophy (2 papers, 2020 to 2025). "Our results showed that inhibiting SLC26A4 suppressed cardiac hypertrophy, as determined by the down-regulation of ANP and BNP and the up-regulation of GSK-3β." (PMID 31998553, 2020). "Inhibiting SLC26A4 significantly elevated the mRNA expression of GSK-3β in PE-induced cardiac hypertrophy models." (PMID 31998553, 2020). "In the present study, we showed that inhibiting SLC26A4 attenuates cardiac hypertrophy by apoptosis and autophagy." (PMID 31998553, 2020). "RT-qPCR results showed that the mRNA expression of SLC26A4 was significantly up-regulated in PE-induced cardiac hypertrophy." (PMID 31998553, 2020). "Our findings revealed that SLC26A4 could become a potential therapeutic target for cardiac hypertrophy." (PMID 31998553, 2020). "Above results reveal that inhibiting SLC26A4 promotes cell apoptosis in cardiac hypertrophy." (PMID 31998553, 2020). "Our study found that SLC26A4 is involved in cardiac hypertrophy and inhibiting SLC26A4 could decrease the release of ANP or BNP and promote the expression of GSK-3β in vivo and in vitro." (PMID 31998553, 2020). "In PE-induced cardiac hypertrophy, we found that SLC26A4 was significantly elevated." (PMID 31998553, 2020). "We showed that siRNA-SLC26A4 treatment could promote apoptosis of cardiomyocytes induced by PE, indicating that inhibiting SLC26A4 could remodel cardiac structure after cardiac hypertrophy through the induction of apoptosis." (PMID 31998553, 2020). "In addition, RT-qPCR results demonstrated that SLC26A4 expression was inhibited in PE-induced cardiac hypertrophy mice injected with siRNA-SLC26A4." (PMID 31998553, 2020). "Our findings revealed that SLC26A4 increases cardiac hypertrophy, and inhibiting SLC26A4 could decrease the release of ANP/BNP and promote the expression of GSK-3β in vitro and in vivo." (PMID 31998553, 2020). "Therefore, SLC26A4 possesses potential value to be a therapeutic target of cardiac hypertrophy, and our study provides new insights into the mechanisms of cardiac hypertrophy." (PMID 31998553, 2020). "We further confirmed whether inhibiting SLC26A4 could reverse PE-induced cardiac hypertrophy." (PMID 31998553, 2020). "However, inhibiting SLC26A4 significantly reversed the increased α-SMA and cell surface area induced by PE, indicating that inhibiting SLC26A4 could attenuate myocardial fibrosis and cardiac hypertrophy." (PMID 31998553, 2020). "Therefore, our results showed that inhibiting SLC26A4 could suppress cardiac hypertrophy by autophagy inactivation of myocardial cells." (PMID 31998553, 2020). "Therefore, inhibiting SLC26A4 could reverse PE-induced cardiac hypertrophy in vivo, indicating that SLC26A4 could become a potential therapeutic target for cardiac hypertrophy." (PMID 31998553, 2020). "Therefore, SLC26A4 could become a potential target for the treatment of cardiac hypertrophy, which provides new insights into the mechanisms and treatment of cardiac hypertrophy." (PMID 31998553, 2020). "Above results suggest that inhibiting SLC26A4 could ameliorate PE-induced cardiac hypertrophy." (PMID 31998553, 2020). "Furthermore, inhibiting SLC26A4 promoted apoptosis of cardiac hypertrophy cells." (PMID 31998553, 2020). "Therefore, in our study, we explored the role of SLC26A4 in cardiac hypertrophy, and whether inhibiting SLC26A4 would markedly improve cardiac hypertrophy." (PMID 31998553, 2020). "We further investigated whether SLC26A4 could affect cell apoptosis in cardiac hypertrophy." (PMID 31998553, 2020). "However, the role of SLC26A4 in cardiac hypertrophy and relevant signaling pathways remain unclear." (PMID 31998553, 2020). "Therefore, in PE-induced cardiac hypertrophy, inhibiting SLC26A4 could attenuate cell autophagy." (PMID 31998553, 2020). "However, the role of SLC26A4 in cardiac hypertrophy and the signaling pathways remain unclear." (PMID 31998553, 2020).
cardiac hypertrophy (continued). "Inhibiting SLC26A4 displayed enhanced autophagy indicated by lower beclin-1 and LC3II/I and higher P62 in PE-induced cardiac hypertrophy." (PMID 31998553, 2020). "However, siRNA-SLC26A4 treatment only slightly attenuated its increased expression levels induced by PE in cardiomyocytes, indicating that high SLC26A4 expression could play an important role in cardiac hypertrophy." (PMID 31998553, 2020). "Therefore, we asked that whether inhibiting SLC26A4 could reverse PE-induced cardiac hypertrophy." (PMID 31998553, 2020). "Also, the expression of SLC26A4, GSK3, cardiac hypertrophy markers including atrial natriuretic peptide (ANP) and brain natriuretic peptide (BNP) was detected through real-time quantitative polymerase chain reaction (RT-qPCR)." (PMID 31998553, 2020). "We found that SLC26A4 was up-regulated in PE-induced H9C2 cells, indicating that SLC26A4 could participate in the processes of cardiac hypertrophy." (PMID 31998553, 2020).
epilepsy (2 papers, 2013 to 2020). A brain disorder characterized by episodes of abnormally increased neuronal discharge resulting in transient episodes of sensory or motor neurological dysfunction, or psychic dysfunction. "While most of genes are known to be related to ASD, ID or epilepsy, ABCC2, CCDC50 and SLC26A4 were not reported to be related to neurodevelopmental disorder according to OMIM." (PMID 32477112, 2020).
hearing disorder (2 papers, 2018 to 2021). A disorder characterized by the partial or complete loss of the ability to detect sounds due to damage to the ear structures or inability of the brain to properly interpret or process the auditory signals it receives from the anatomic structures of the ear. "The presence of the two (c.343T>G and c.1301C>A) exonic SLC26A4 sequence variations was assessed in 125 healthy volunteers with no self-reported hearing disorders using custom designed genotyping assays." (PMID 29320412, 2018).
lung mucoepidermoid carcinoma (2 papers, 2019 to 2022). "Moreover, IL-17A is known to stimulate upregulation of SLC26A4, an anion exchange protein which is known to induce goblet cell hyperplasia in human lung mucoepidermoid carcinoma cells and murine airway epithelial cells." (PMID 35773318, 2022).
Sensorineural hearing impairment (2 papers, 2014 to 2024). A type of hearing impairment in one or both ears related to an abnormal functionality of the cochlear nerve. "Previous studies have revealed that homozygous (biallelic variation) or compound heterozygosity for c.919-2A > G and c.2168 A > G in the SLC26A4 gene was the molecular genetic etiology of sensorineural hearing impairment." (PMID 38378613, 2024).
thyroid dysgenesis (2 papers, 2018 to 2023). "Interestingly, despite being classically implicated in thyroid hormonogenesis, SLC26A4 variations were reported also in patients with apparent thyroid dysgenesis." (PMID 36071330, 2023).
thyroid tumor (2 papers, 2014 to 2022). A benign or malignant neoplasm affecting the thyroid gland. "This association was validated functionally by low SLC26A4’s mRNA expression and low immunostaining for pendrin in cancerous thyroid tumors." (PMID 36553459, 2022). "Interestingly, the 5′ region of the SLC26A4 gene was found to be hyper-methylated as an early event in the majority of malignant human thyroid tumors, presumably accounting for at least part of the decreased SLC26A4 expression in these tumors." (PMID 24795638, 2014).
allergic rhinitis (1 paper, 2024). Inflammation of the nasal mucous membranes caused by an IgE-mediated response to external allergens. "For example, SLC26A4 has been shown to be highly expressed in the nasal mucosa of patients with chronic rhinosinusitis with nasal polyps(CRSwNP) and allergic rhinitis (AR)." (PMID 39100210, 2024).
Areflexia (1 paper, 2024). Absence of neurologic reflexes such as the knee-jerk reaction. "Among the 15 patients with SLC26A4 variants, eight (47%) exhibited semicircular canal dysfunction (one bilateral areflexia, two unilateral areflexia or hyporeflexia in each ear, one bilateral hyporeflexia, one unilateral areflexia, and one unilateral hyporeflexia)." (PMID 38720048, 2024).
autism (1 paper, 2022). Persistent deficits in social interaction and communication and interaction as well as a markedly restricted repertoire of activity and interest as well as repetitive patterns of behavior. "The patient had poor social communication and was suspected autistic, however, no reports have shown the correlations between the SLC26A4 gene and autism." (PMID 35741772, 2022). "Due to the lack of literature connecting SLC26A4 with autism, CMA and WES were performed." (PMID 35741772, 2022).
benign prostatic hyperplasia (1 paper, 2022). A non-cancerous nodular enlargement of the prostate gland. "In our own Xiangya cohort, the SLC26A4 expression in PCa samples was lower than that in benign prostatic hyperplasia tissues at both mRNA and protein levels, which was inconsistent with the results of the TCGA-PRAD cohort." (PMID 35836192, 2022).
bronchiectasis (1 paper, 2023). Segmental, irreversible dilation of the bronchial tree resulting in the accumulation of secretions which leads to obstruction. "We remind clinicians to pay attention to the possibility of bronchiectasis in patients with SLC26A4 gene mutations." (PMID 36699303, 2023). "However, there is no case report of bronchiectasis caused by SLC26A4 gene mutations." (PMID 36699303, 2023).
conductive hearing loss (1 paper, 2014). "No statistical difference in the KCNJ10 c.812G>A and c.1042C>T mutations was observed between the normal-hearing group and the NSEVA cases with zero, one, or two mutations in SLC26A4, patients with inner ear malformation, or patients with conductive hearing loss (χ2 = 6.287, P = 0.179)." (PMID 25372295, 2014). "It was found in patients with NSEVA who carried no mutation, a monoallelic mutation, or two mutations in SLC26A4; in patients with inner ear malformation; in patients with conductive hearing loss; and in normal-hearing individuals." (PMID 25372295, 2014).
gastric cancer (1 paper, 2020). A primary or metastatic malignant neoplasm involving the stomach. "SLC26A4-AS1was found to be associated with overall survival in gastric cancer." (PMID 32377223, 2020).
glioma (1 paper, 2015). A benign or malignant brain and spinal cord tumor that arises from glial cells (astrocytes, oligodendrocytes, ependymal cells). "This assay system consisted of donor and acceptor cells from LN215 glioma cells that expressed SLC26A4 and yellow fluorescent protein-H148Q/I152L (YFPQL), respectively." (PMID 26444544, 2015).
Graves' hyperthyroidism (1 paper, 2023). "The genes related to the antithyroid effects of long-term iodine loading are Slc5a5, Slc26a4, Duox2, and Duoxa2, in addition to Tpo, Dio1, and Slco4a1, which are upregulated in Graves' hyperthyroidism." (PMID 36565031, 2023).
Horner syndrome (1 paper, 2022). Horner's syndrome is a rare condition characterized by miosis (constriction of thepupil), ptosis (drooping of the upper eyelid), and anhidrosis (absence of sweating of the face). "Evaluations for localization of Horner syndrome on the patient and Sanger sequencing of SLC26A4 on the family members were performed." (PMID 35204885, 2022).
hydrops (1 paper, 2011). "Examination of the cochlear duct from 4-week-old mice revealed severe endolymphatic hydrops with dilatation of scala media in Slc26a4tm1Dontuh/tm1Dontuh mice, compared to Slc26a4+/+ mice." (PMID 21811566, 2011).
Hypoglycemia (1 paper, 2016). A decreased concentration of glucose in the blood. "Moreover, we were able to point out several glycoproteins (Fibulin1, Versican, Fibromodulin) linked to the extracellular matrix (ECM), many crystallins and few solute carriers (Slc26a4, Slc6a13) whose expression was modified by hypoglycemia." (PMID 26918849, 2016).
Hypokalemia (1 paper, 2022). An abnormally decreased potassium concentration in the blood. "However, the diagnostic role of SLC26A4 (pendrin) mutation in Pendred syndrome with hypokalemia remains to be clarified." (PMID 36107570, 2022). "Therefore, it can be speculated that the clinical manifestations of hypokalemia are associated with SLC26A4 gene mutation." (PMID 36107570, 2022).
Meniere disease (1 paper, 2021). A disease of the inner ear (labyrinth) that is characterized by fluctuating sensorineural hearing loss; tinnitus; episodic vertigo; and aural fullness. "Specifically, in a large cohort of 890 patients with sporadic Meniere disease, enrichment in rare missense exonic variants in SLC26A4 and KCNJ10 genes has been reported when their minor allele frequency (MAF) was compared to reference data from ExAC, non-Finnish European, and Spanish populations." (PMID 34562878, 2021).
nasal polyps (1 paper, 2024). "In clinical studies, patients with nasal polyps show increased SLC26A4 expression in eosinophilic chronic rhinosinusitis." (PMID 38673775, 2024). "SLC26A4 is mainly expressed in the epithelial membrane of turbinate mucosa and nasal polyps." (PMID 38673775, 2024).
nodular goiter (1 paper, 2022). Goiter characterized by discrete tissue mass(es) that may or may not produce thyroid hormones. "However, one patient (patient code 1091) with a homozygous c.2027T>A p.(Leu676Gln) pathogenic variant in the SLC26A4 gene underwent surgery on the thyroid gland for nodular goiter (25%)." (PMID 36499699, 2022).
prostate carcinoma (1 paper, 2022). A carcinoma that arises from epithelial cells of the prostate gland. "Our study uniquely found that SLC26A4 was highly associated with HRD in prostate cancer." (PMID 35836192, 2022). "Unfortunately, the prostate cancer single-cell cohort there didn’t provide the expression data for SLC26A4, hampering our understanding of the correlations in prostate cancer." (PMID 35836192, 2022). "SLC26A4 mRNA surpassed baseline total prostate specific antigen (PSA) value in predicting prostate cancer (AUC = 0.845)." (PMID 35836192, 2022). "And SLC26A4 demonstrated excellent performance in predicting HRD in the context of prostate cancer (AUC = 0.911)." (PMID 35836192, 2022). "Compared to BPH tissues, SLC26A4 mRNA expression levels and IHC scores were decreased in prostate cancer samples." (PMID 35836192, 2022). "Finally, DNA methylation of SLC26A4 (by Illumina HumanMethylation450 BeadChip) was increased in prostate cancer tissues than the normal controls." (PMID 35836192, 2022). "Nevertheless, the lack of prostate cancer single-cell cohort with SLC26A4 expression data hampered our understanding of its functions in PCa." (PMID 35836192, 2022). "Furthermore, SLC26A4 was significantly down-regulated in prostate cancer tissues with HRD than those without HRD at mRNA and protein levels." (PMID 35836192, 2022).
thalassemia (1 paper, 2025). An inherited blood disorder characterized by a decreased synthesis of one of the polypeptide chains that form hemoglobin. "The most common variants in HL carriers were c.235delC of GJB2, c.919‐2A>G of SLC26A4, and m.1555A>G of MT‐RNR1, and those in thalassemia carriers were ‐SEA, ‐α3.7, and HBB:c.126_129delCTTT." (PMID 39988971, 2025).
Usher syndrome type 1 (1 paper, 2014). A syndrome characterized by congenital, bilateral, severe sensorineural hearing loss, abnormalities in the vestibular system, and adolescent-onset retinitis pigmentosa. "In particular, from the prognostic perspective, we can expect successful results of CI in hereditary deafness with mutation of specific genes, such as, GJB2, SLC26A4, mitochondrial mutations, OTOF, Usher syndrome type I, DFNA9 (COCH), and DFNA17 (MYH9)." (PMID 25373420, 2014).
uveal melanoma (1 paper, 2022). A melanoma derived from melanocytes of the uveal tract. "Moreover, SLC26A4 was a risk for uveal melanoma (UVM) and LGG." (PMID 35836192, 2022).
Vestibular schwannoma (1 paper, 2020). A vestibular schwannoma (also known as acoustic neuroma, acoustic neurinoma, or acoustic neurilemoma) is a benign, usually slow-growing tumor that develops from the VIIIth cranial nerve supplying the inner ear. "Based on the radiological evaluation, two affected subjects carrying SLC26A4 variants and one affected subject carrying NF2 variants in the GD group had bilateral enlarged vestibular aqueduct and bilateral vestibular schwannoma, respectively." (PMID 32238869, 2020).
Wilson disease (1 paper, 2023). A very rare inherited multisystemic disease presenting non-specific neurological, hepatic, psychiatric or osseo-muscular manifestations due to excessive copper deposition in the body. "The common mutation spectrum of GJB2 and SLC26A4 in this study was consistent with previous literature reports of the Chinese population, while the mutation spectrum of ATP7B was inconsistent with a research report of Chinese patients with Wilson's disease." (PMID 37031186, 2023).